MERTK (MER proto-oncogene, tyrosine kinase)
Diseases named in the same sentence as MERTK in open-access papers (continued):
Sharing a sentence is not in itself a finding about the gene and the disease.
prostate carcinoma (7 papers, 2018 to 2025). A carcinoma that arises from epithelial cells of the prostate gland. "Additionally, MerTK expression on prostate cancer tumor-associated macrophages is unknown, although MerTK expression in prostate cancer cell lines and mouse models has been investigated." (PMID 37644281, 2023). "Another study identified MERTK as a driver of bone metastasis in prostate cancer in a screening of human samples." (PMID 38203403, 2023). "Most importantly, the depletion of MERTK in prostate cancer cells and subsequent inoculation in vivo increased metastasis-free survival without affecting the growth kinetics of the primary tumor." (PMID 38203403, 2023). "Phosphorylated MerTK increased in LNCaP-efferocytosing M2 macrophages, suggesting a role in prostate cancer efferocytosis." (PMID 37644281, 2023). "High MERTK expression was found more frequently in prostate cancer bone metastatic tissue compared with the primary tumor." (PMID 38203403, 2023). "Authors have shown that the knockdown of MERTK in prostate cancer cells induced transcription factors that promote cancer dormancy, such as SOX2, NR2F1, and NANOG." (PMID 38203403, 2023). "Phosphorylated MerTK (pMerTK) increases 1 h following apoptotic LNCaP cell addition in M2 THP-1 macrophages, indicating a role of MerTK in prostate cancer cell efferocytosis specifically." (PMID 37644281, 2023). "We explored targeting MerTK in vivo in the prostate cancer genetically engineered mouse model hi-myc." (PMID 37644281, 2023). "We conclude that MerTK is the strongest candidate among the TAM receptors for blocking prostate cancer cell efferocytosis." (PMID 37644281, 2023). "We explored targeting MerTK to block prostate cancer efferocytosis using a MerTK targeting antibody in vitro and an in vivo knockout mouse model." (PMID 37644281, 2023). "Targeting MerTK with antibody Mer590 decreased LNCaP efferocytosis by M2 HMDMs, establishing the role of MerTK in prostate cancer efferocytosis." (PMID 37644281, 2023). "MERTK stimulates the reactivation of dormant prostate cancer cells through MAP kinase-dependent mechanism, which involves p27, pluripotency transcription factors, and histone methylation." (PMID 29616190, 2018). "Recent report suggests that the TAM family of receptor tyrosine kinases TYRO3, AXL, and MERTK have a potential role in dormancy regulation in prostate cancer." (PMID 29616190, 2018). "Interestingly, the loss of function of MerTK increases M1-like anti-tumor phenotypes and reduces M2-type pro-tumor macrophages in the high-MYC prostate cancer mouse model as well as decreases M2-mediated efferocytosis in prostate cancer LNCaP cells." (PMID 38891056, 2024). "In prostate cancer, MERTK has also been described as a regulator of tumor cell dormancy." (PMID 38203403, 2023). "Additionally, this study aims to demonstrate that targeting MerTK decreases prostate cancer efferocytosis and promotes an anti-tumor immune infiltrate." (PMID 37644281, 2023). "Tyro3, Axl, and MerTK mediate efferocytosis by macrophages, but their role in prostate cancer cell efferocytosis is unknown." (PMID 37644281, 2023). "Based on our in vitro data, targeting MerTK on macrophages decreased prostate cancer efferocytosis." (PMID 37644281, 2023). "We investigate targeting MerTK to decrease efferocytosis of prostate cancer cells in vitro." (PMID 37644281, 2023). "We sought to understand MerTK’s role in tumor growth and immune infiltration in the FVB hi-myc prostate cancer model." (PMID 37644281, 2023). "We hypothesize efferocytosis in the prostate cancer TME is a tumor-promoting function of macrophages and that targeting MerTK-mediated efferocytosis will slow prostate cancer growth and promote an anti-tumor immune infiltrate." (PMID 37644281, 2023).
prostate carcinoma (continued). "However, the same research group reported a further study demonstrating that the shRNA-mediated MERTK knockdown, but not Axl and Tyro3, resulted in the upregulation of stemness-associated genes, anti-apoptosis, G1-G0 arrest, and the characteristics of dormancy in prostate cancer cells." (PMID 33562150, 2021). "Given that MerTK only had a minor role in prostate cancer efferocytosis in vitro, targeting macrophage MerTK may not be sufficient to inhibit prostate cancer growth." (PMID 37644281, 2023). "Additionally, high MerTK expression in M2s may support prostate cancer efferocytosis through a non-kinase function." (PMID 37644281, 2023).
Alzheimer disease (6 papers, 2018 to 2026). A progressive, neurodegenerative disease characterized by loss of function and death of nerve cells in several areas of the brain leading to loss of cognitive function such as memory and language. "Mer tyrosine kinase (MerTK) activity necessary for amyloid-stimulated phagocytosis strongly implicates that MerTK dysregulation might contribute to chronic inflammation implicated in Alzheimer’s disease (AD) pathology." (PMID 29530050, 2018). "Subcluster 2 expressed high levels of white matter associated genes (NRP1, MERTK, and NCKAP5) while subcluster 3 displayed a disease‐associated signature (STARD13, MITF, GPNMB, and DPYD) previously observed in Alzheimer's disease (AD) and Multiple Sclerosis (MS)." (PMID 41283828, 2026). "However, in Alzheimer’s disease (AD), both MEGF10 and MERTK are downregulated, resulting in impaired elimination of excitatory synapses and dysregulated synaptic transmission." (PMID 40723783, 2025).
injury (6 papers, 2018 to 2026). Damage inflicted on the body as the direct or indirect result of an external force, with or without disruption of structural continuity. "We have also observed that restoring MerTK protein expression by treatment with TNF-α processing inhibitor-0 (TAPI-0) can efficiently prevent the inflammatory cascade during acute lung injury." (PMID 29530050, 2018). "We identify a hepatoprotective, MerTK+, macrophage phenotype that evolves during the resolution phase following ALF and represents a novel immunotherapeutic target to promote resolution responses following acute liver injury." (PMID 28450389, 2018).
ischemic stroke (6 papers, 2020 to 2025). A stroke disorder caused by obstruction of blood flow to the brain, due to thrombotic (local blood clot formation) or embolic (due to a blood clot or other material traveling from another site) event. "Microglia/macrophages phagocytose viable neurons via milk fat globule‐EGF factor VIII (MFG‐E8) and MER proto‐oncogene tyrosine kinase (MERTK) during the acute phase of ischemic stroke, and inhibition of this process prevents delayed loss of functional neurons and death." (PMID 38727249, 2024). "For example, we found that that knockout of MFG-E8 or MerTK could reduce delayed neuronal loss after ischemic stroke in mice and rats respectively." (PMID 35216419, 2022). "Using a transient middle cerebral artery occlusion (tMCAO) model of ischemic stroke, we demonstrate that eCIRP is released into the cerebrospinal fluid and microglial expression of crucial efferocytic receptor MerTK decreases in tMCAO mice." (PMID 40766256, 2025). "To investigate the effects of MEGF10 and MERTK on dendritic spine structure after ischemic stroke, we performed Golgi-Cox staining to visualize neuronal dendritic spines in MEGF10WT, MERTKWT, C-MEGF10KO, C-MERTKKO, A-MEGF10KO, and A-MERTKKO mice." (PMID 34836962, 2021). "By specifically deleting MEGF10 and MERTK phagocytic receptors, we determined that inhibiting phagocytosis of microglia/macrophages or astrocytes in ischemic stroke improved neurobehavioral outcomes and attenuated brain damage." (PMID 34836962, 2021). "MEGF10 and MERTK were also detected in astrocytes of mice after ischemic stroke and hemorrhagic stroke." (PMID 34836962, 2021). "Here, the authors show in a murine model of ischemic stroke that inhibition of phagocytosis by MEGF10 and MERTK deletion in microglia and astrocytes attenuated damage and improved neurological outcomes by preventing synapse loss." (PMID 34836962, 2021).
liver disease (6 papers, 2018 to 2024). "In this longitudinal study, we found an association between the presence of the MERTK rs4374383 A allele and a reduced risk for liver disease progression in HCV-infected patients, whereas the G allele increased the risk." (PMID 30477195, 2018). "Starting from this evidence, we investigated whether the MERTK variant A>G can influence the risk of progression of liver disease, in patients with chronic infection sustained by hepatitis viruses (C or B) or with nonalcoholic steatohepatitis (NASH)." (PMID 36003399, 2022). "The impact of this SNP on liver disease seems to be due to the loss-of-function of the rs4374383 G > A variant, a non-coding variant located within an intronic region of the MERTK gene, which could reduce HSC activation when the rs4374383 A-allele variant is present." (PMID 30477195, 2018). "Conclusions: our results confirm that MERTK represents a genetic biomarker for progression of liver disease and are suggestive of translational relevance for the study of downstream pathways involved in fibrogenesis and hepatocarcinogenesis." (PMID 36003399, 2022). "The aim of our work was to investigate the functional mechanism that links MerTK and progression of liver disease in CHC patients especially in neoplastic direction." (PMID 36003399, 2022). "Besides being involved in immune homeostasis, MERTK and AXL were also associated with deleterious processes in some liver diseases." (PMID 37004869, 2023). "Therefore, all in all, MERTK plays an important role in the fibrotic process of liver diseases." (PMID 30477195, 2018). "However, how MerTK can condition the progression of liver disease remains unknown." (PMID 36003399, 2022).
lupus (6 papers, 2013 to 2025). "Whereas the cleavage of MerTK may be critical for the accumulation of AC-derived autoantigens and production of pathogenic lupus-specific autoantibodies, the cleavage of Axl could be more generally related to uninhibited TLR activation and production of IFN-α/β and other proinflammatory cytokines." (PMID 24325951, 2013). "Given that ESRD is one of the main predictors of mortality in lupus and the ability to predict progression to ESRD eventually may yield therapeutic targets to prevent it, our results support MERTK as a promising target for preventing ESRD in patients with LN." (PMID 36332927, 2022). "In addition, it has been noted in human MΦ from patients with systemic lupus erythematosus that the level of soluble receptor and membrane-bound forms of MERTK do not correlate." (PMID 38517345, 2024).
choroideremia (5 papers, 2018 to 2025). Choroideremia (CHM) is an X-linked chorioretinal dystrophy characterized by progressive degeneration of the choroid, retinal pigment epithelium (RPE) and retina. "Localized iatrogenic detachment of degenerate retina has been performed for the subretinal delivery of adeno-associated viral gene therapy vectors for RPE65 and MERTK-associated RP,24, 25, 26, 27 and choroideremia." (PMID 29110946, 2018). "Several monogenic forms of retinal degeneration are also caused by mutations in genes that are expressed in the RPE; for example, mutations in MERTK, which cause retinitis pigmentosa, CHM, which cause choroideremia, and MYO7A which cause Usher syndrome type 1B." (PMID 35309899, 2022). "This modality of treatment has shown efficacy in clinical trials treating RPE65-associated Leber congenital amaurosis (LCA), CHM-associated choroideremia, CNGA3-related achromatopsia, and MERTK-associated retinitis pigmentosa." (PMID 36012955, 2022).
fibrosis (5 papers, 2019 to 2025). the formation of excess fibrous connective tissue in an organ or tissue in a reparative or reactive process. "rs4374383 AA correlates with lower MerTK expression and hepatoprotective functions, as a lower percentage of those patients suffered from stage F2–F4 fibrosis compared to patients presenting the rs4374383 GG/AG SNPs." (PMID 34771611, 2021). "MERTK was overexpressed in the liver of NAFLD patients with F2-F4 fibrosis, mainly in HSCs and macrophages (but not in hepatocytes)." (PMID 31583026, 2019).
heart failure (5 papers, 2017 to 2026). Inability of the heart to pump blood at an adequate rate to meet tissue metabolic requirements. "GAS6 administration during the perioperative period enhances MerTK+ cardiac macrophages and angiogenesis, limiting progression to heart failure." (PMID 39195894, 2024). "In heart disease, MerTK expression is significantly higher in aortic valve stenosis, atrial fibrillation-metabolic syndrome, metabolic syndrome, and heart failure-idiopathic cardiomyopathy." (PMID 38341954, 2024). "Finally, based on our proteomics from primary human aortic ECs, we validated the functions of MerTK in several human diseases, such as cancer, aging, kidney failure and heart failure." (PMID 38341954, 2024). "A key focus is how efferocytic dysfunction (e.g., MerTK cleavage, CD47 upregulation, Lgmn blockade) triggers a self-perpetuating vicious cycle of failed clearance, sustained inflammation, and repair collapse, leading to adverse remodeling and heart failure." (PMID 41878419, 2026).
osteosarcoma (5 papers, 2022 to 2024). A usually aggressive malignant bone-forming mesenchymal neoplasm, predominantly affecting adolescents and young adults. "Blocking the MerTK-mediated efferocytosis pathway significantly suppresses osteosarcoma progression and immune tolerance." (PMID 39359731, 2024). "Additionally, MERTK mediates macrophage efferocytosis in osteosarcoma and induces an immunosuppressive microenvironment by inducing M2 polarization and promoting programmed death-ligand 1 (PD-L1) expression in macrophages." (PMID 38203403, 2023). "Therefore, inhibiting MerTK could be an effective approach to enhance osteosarcoma immunotherapy." (PMID 39359731, 2024). "Treatment with a MERTK inhibitor in an in vivo model of osteosarcoma reduced tumor growth but did not affect the number of lung metastases." (PMID 38203403, 2023).
ovarian carcinoma (5 papers, 2017 to 2025). A malignant neoplasm originating from the surface ovarian epithelium. "In terms of protein expression, we found that AXL was significantly up‐regulated in renal clear cell carcinoma, CD47 was significantly up‐regulated in ovarian cancer, pancreatic cancer and endometrial cancer, and MERTK was significantly up‐regulated in both ccRCC and pancreatic cancer." (PMID 40576208, 2025). "Further signalling pathways influencing COL1A1 transcription via (at least to some extent) TGFβ are Mer Tyrosine Kinase (MERTK), PKCε, Ovarian cancer G-protein coupled Receptor-1 (OGR1), β-catenin, and osteopontin (more details can be found in Appendix A, Table A5)." (PMID 37373151, 2023). "We found that AXL and MERTK were expressed at higher levels in liver tissue, lung tissue, endometrial tissue; CD47 was up‐regulated in breast tissue, lung tissue, ovarian cancer, pancreatic cancer and endometrial cancer; and HAVCR2 showed higher expression in renal clear cell carcinoma." (PMID 40576208, 2025). "Among the CSC-related genes, to our knowledge no data are available on the role of MERTK in ovarian cancer." (PMID 26910918, 2017).
Sepsis (5 papers, 2021 to 2025). Sepsis is defined as life-threatening organ dysfunction caused by a dysregulated host response to infection. "This dual role suggests that moderate activation of MERTK in the early stages of sepsis may help delay disease progression." (PMID 40177399, 2025). "This suggests that MERTK may be a therapeutic target for interventions aimed at mitigating the severity of sepsis." (PMID 40177399, 2025). "Pharmacological inhibition of ADAM8 could preserve MerTK-mediated efferocytosis, reduce inflammation and apoptosis, and improve cardiac outcomes in sepsis." (PMID 41169382, 2025). "However, some data have highlighted the importance of MERTK activation in the clearance of apoptotic cells, suppression of proinflammatory cytokine production, and prevention of autoreactive lymphocyte proliferation, indicating a dual role for MERTK in the prognosis of patients with sepsis." (PMID 40177399, 2025). "In contrast to MERTK, which was regulated similarly in the two mouse strains, LAIR-1 expression was differentially regulated in C57BL/6J and BALB/c in the context of sepsis, with LAIR-1 expression significantly upregulated only in CLP C57BL/6 CD11b+Ly6Chigh monocytes." (PMID 39506629, 2024). "As growth arrest-specific gene 6 (Gas6)/Tyro3, Axl, MerTK (TAM) receptors signaling has shown immunomodulatory activity in sepsis, here we sought to determine whether Gas6 protein injection could mitigate MOF in a cecal slurry mouse model of sepsis." (PMID 33803290, 2021).
triple-negative breast carcinoma (5 papers, 2022 to 2026). An invasive breast carcinoma which is negative for expression of estrogen receptor (ER), progesterone receptor (PR), and human epidermal growth factor receptor 2 (HER2). "We identified the TAM (Tyro3, Axl, and MerTK) RTKs as a crucial therapeutic vulnerability in Triple-negative breast cancer (TNBC)." (PMID 38927958, 2024).
brain ischemia (4 papers, 2017 to 2023). Diminished or absent blood supply to the brain caused by obstruction (thrombosis or embolism) of an artery resulting in neurologic damage. "This may be consistent with delayed neuronal loss after brain ischemia being due to Gal-3–, Neu1-, and MerTK-mediated microglial phagocytosis." (PMID 28500071, 2017). "A study had reported that transient brain ischemia caused a delayed neuronal loss, accompanied by microglial phagocytosis of neurons, which was prevented by genetic inactivation of either MFG-E8 or MerTK." (PMID 32733436, 2020). "MerTK or MFG‐E8, both of which mediate PS‐recognition, are upregulated by microglia after brain ischemia and enhance delayed neuronal death." (PMID 35751629, 2022). "Recent studies have also shown that after brain ischemia, microglia express the phagocytosis related proteins Milk fat globule EGF-like factor-8 (MFG-E8) and Mer receptor tyrosine kinase (MerTK) affecting still living and viable neurons at 3 to 7 days after focal brain ischemia." (PMID 36818562, 2023). "Both MerTK and MEF‐E8 are transiently upregulated following transient brain ischemia." (PMID 35751629, 2022).